KIF25-AS1 (KIF25 antisense RNA 1)
Synonyms: C6orf54; NCRNA00300; HGC6.1.1; HGC6.3
Gene: Long non-coding RNA gene on chromosome 6 (167,970,316 to 167,997,110, reverse strand). Ensembl gene ENSG00000229921.
Diseases named in the same sentence as KIF25-AS1 in open-access papers:
KIF25-AS1 is named in the same sentence as 2 diseases in open-access papers, as found by Europe PMC text mining. Sharing a sentence is not in itself a finding about the gene and the disease. The quoted sentences say what the papers report.
tumours (1 paper, 2023). "For AC006369.2, AC006037.2, KIF25AS1, and AC002511.2, there is no research to explore their role in tumours." (PMID 36844873, 2023).
KIF25-AS1 also shares sentences with these, for which no sentence is quoted: liver cancer (1 paper).